JUNB (JunB proto-oncogene, AP-1 transcription factor subunit)
Diseases named in the same sentence as JUNB in open-access papers (continued):
Sharing a sentence is not in itself a finding about the gene and the disease.
atherosclerosis (4 papers, 2022 to 2025). A disease characterized by the build-up of fatty material and calcium deposition in the arterial wall resulting in partial or complete occlusion of the arterial lumen. "FOSB was upregulated in plaque only, similarly to CD4+ C3, and JUNB expression was increased in PSA compared to atherosclerosis." (PMID 38665903, 2023). "Whether TLR2/mtROS/JunB-Fra-1/MMP2 signal axis participates in C. pneumoniae infection-induced atherosclerosis development remains unknown." (PMID 35493076, 2022). "Furthermore, in ApoE‐/‐ mice model of C. pneumoniae infection-induced atherosclerosis, the expressions of JunB, Fra-1 and MMP2 in VSMCs in atherosclerotic lesions were also increased compared with mock infected ApoE‐/‐ mice." (PMID 35493076, 2022). "Taken together, C. pneumoniae infection may promote VSMC migration and atherosclerosis development by increasing the level of mtROS through TLR2 to activate the JunB-Fra-1/MMP2 signaling pathway." (PMID 35493076, 2022). "Accordingly, reducing the level of mtROS to block C. pneumoniae infection-induced VSMC migration-related signal axis, JunB-Fra-1/MMP2 signal axis, may become a potential treatment target for C. pneumoniae infection-induced atherosclerosis." (PMID 35493076, 2022).
diabetes (4 papers, 2009 to 2022). "JUNB also elevates the expression of IRE1α in osteoblastogenesis, and IRE1α promotes the wound healing in diabetes." (PMID 32845084, 2020). "The expression of transcription factor JUNB was significantly down-regulated in the model of muscle atrophy induced by diabetes, denervation and starvation." (PMID 32868811, 2020). "Moreover, JUNB has been shown to increase the expression of inositol‐requiring enzyme 1α (IRE1α) in osteoblastogenesis, while IRE1α has been reported to accelerate the process of wound healing in diabetes." (PMID 32845084, 2020).
glioma (4 papers, 2016 to 2024). A benign or malignant brain and spinal cord tumor that arises from glial cells (astrocytes, oligodendrocytes, ependymal cells). "Glioma-associated DEGs DOCK6, ILK, MGMT, NOTCH4 were up-regulated and FGF10, JAK1, JUNB, RHOB were down-regulated uniquely in the mouse." (PMID 29352201, 2018). "In glioma cells, Fra-1 was found to upregulate and dimerize with JunB, contributing to the malignant phenotype." (PMID 26734995, 2016). "Data from GEPIA2 also showed frequently increased FOS, JUNB, JUN, and ATF3 in glioma, especially GBM samples, compared to normal brain tissues." (PMID 39257581, 2024). "Other genes uniquely altered in mouse gliomas (e.g. NOTCH4, FGF10, JUNB, RHOB) may contribute further to murine-specific differences in glioma biology." (PMID 29352201, 2018).
head and neck squamous cell carcinoma (4 papers, 2016 to 2024). A squamous cell carcinoma that arises from any of the following anatomic sites: lip and oral cavity, nasal cavity, paranasal sinuses, pharynx, larynx, and salivary glands. "As a key member of the AP-1 family, JUNB has been shown to promote invasion and distant metastasis in head and neck squamous cell carcinoma." (PMID 37337631, 2023).
inflammatory skin disease (4 papers, 2018 to 2025). Inflammatory skin disorders covers a broad category that includes many conditions ranging in severity, from mild itching to grave medical health complications These disorders are common in people of all ages and races. "The crucial involvement of JunB in inflammatory skin diseases has been well documented in the literature." (PMID 38384322, 2023). "Taken together, these findings indicate a critical role for JunB in skin homeostasis and—in case of JunB deletion—results in development of an inflammatory skin disorder sharing features with seborrheic dermatitis." (PMID 30143626, 2018).
preeclampsia (4 papers, 2014 to 2021). Preeclampsia is a hypertensive disorder of pregnancy that is characterized by new-onset hypertension with proteinuria presenting after 20 weeks of gestation, and depending on mild or severe forms may initially present with severe headache, visual disturbances, and hyperreflexia. "We also observed high DMC density regions in genes for which placental DNAm and/or expression differences have been associated with preeclampsia, including INHBA, JUNB, TEAD3, NDRG1, and CGA." (PMID 33407091, 2021). "In contrast, JUNB is downregulated in placenta-derived Mesenchymal Stromal Cells from the woman with preeclampsia, suggesting this gene plays a critical role during pregnancy and preeclampsia." (PMID 34867473, 2021). "Among the transcription regulatory genes in module M2, ARNT2, BCL6, and JUNB were highly expressed in preterm but not in term preeclampsia, suggesting that these might play a role only in the pathology of preterm cases." (PMID 30135684, 2018).
triple-negative breast carcinoma (4 papers, 2017 to 2025). An invasive breast carcinoma which is negative for expression of estrogen receptor (ER), progesterone receptor (PR), and human epidermal growth factor receptor 2 (HER2). "In triple-negative breast cancer, AP-1 family member JUNB and STAT3 cooperatively recruit YAP, which acts as a transcriptional co-activator for both complexes, thereby enhancing oncogenic transcriptional outputs and correlating with poor clinical outcomes." (PMID 40673277, 2025). "Genes regulated by YAP, TAZ, JUNB, and TEAD and association of various classes of YAP/TAZ target site with differences in overall survival in triple-negative breast cancer patients." (PMID 34463254, 2021).
bladder cancer (3 papers, 2022 to 2025). "Considering the essential roles of JUNB revealed by scRNA-seq and the immunological feature of bladder cancer, we decided to explore the extensive molecular mechanisms in this specific cancer." (PMID 35812726, 2022). "Functional experiment results demonstrated the upregulated JUNB in bladder cancer tissues and low-immunity-score tissues." (PMID 35812726, 2022). "Furthermore, correlation analysis of T-cell inflamed and hyperprogression predicted the harmful effect of ICIs treatment in bladder cancer with upregulated JUNB." (PMID 35812726, 2022). "To investigate the protein expression profiles of six genes (ABCA7, HOOK2, JUNB, RHOB, VMP1, and ACTG1) that significantly impact both DSS and PFI in bladder cancer patients, we conducted Western blot analyses using SV-HUC-1 and 5637 cell lines." (PMID 40574864, 2025).
breast tumors (3 papers, 2020 to 2022). "Comprehensive characterization of the JUNB-deficient tumor microenvironment revealed a strong influx of myeloid cells into primary breast tumors and lungs at early metastatic stage." (PMID 34282521, 2021). "In addition, JUNB protein levels correlated with cyclin E1 and TGFB2 protein levels, suggesting that high JUNB protein levels may also promote aggressiveness of breast tumors by positively controlling their expression with consequences on both cell proliferation and invasion." (PMID 36494864, 2022).
colon carcinoma (3 papers, 2012 to 2023). "MALAT1 is also increased in colon cancer cells, directly binding to miR-663a, thus acting as a competing endogenous lncRNA; as a result, important cancer-related miR-663a targets (TGFB1, PIK3CD, P21, JunB, and JunD) were affected." (PMID 32183400, 2020). "We then explored the mechanism by which PES1 expression is controlled in human colon cancers and demonstrated that c-Jun, but not JunB, JunD, c-Fos, or mutant c-Jun, positively regulated PES1 promoter transcription activity." (PMID 22860098, 2012).
colorectal cancer (3 papers, 2019 to 2025). A primary or metastatic malignant neoplasm that affects the colon or rectum. "We discovered, using mass spectrometry proteomics of DLD-1 colorectal cancer cells, that a partially purified inactivator from L16943 induced JunB and other AP-1 family members." (PMID 40909631, 2025). "In recurrent colorectal cancers, the levels of positive regulators of SERPINB2, such as TNF (Z-score = 5.021, p-value = 0.301), JUNB (Z-score = 1.533, p-value = 0.00515) and ERK (Z-score = 3.763, p-value = 0.171), were also increased." (PMID 30965654, 2019).
endometriosis (3 papers, 2020 to 2025). The growth of functional endometrial tissue in anatomic sites outside the uterine body. "In endometriosis, JUNB collaborates with AP-1 members (e.g., FOS, FOSB) to drive early-stage M1 polarization and inflammation, mirroring our findings in denervated muscle." (PMID 40917776, 2025). "Conversely, late-stage endometriosis shifts toward M2 polarization, emphasizing JUNB’s context-dependent role in immune modulation." (PMID 40917776, 2025). "In women with endometriosis, upregulation of JUNB mRNA, FOS mRNA and FOS protein in secretory endometrium was reported." (PMID 32933042, 2020).
esophageal cancer (3 papers, 2009 to 2025). A primary or metastatic malignant neoplasm involving the esophagus. "In order to analyze the impact of the expression of cJUN and JUNB for esophageal cancer patients, we divided the patients based on their expression levels of the two transcription factors (cJUN: n = 208 positive; JUNB: n = 170 positive)." (PMID 40701988, 2025). "Present investigation provides evidence of a constitutively activated AP-1 in esophageal cancers and demonstrates involvement of JunB, JunD and cFos as major DNA binding partners whereas it clearly negates the role of canonical AP-1 partner, cJun." (PMID 19758438, 2009).
ischemic stroke (3 papers, 2022 to 2025). A stroke disorder caused by obstruction of blood flow to the brain, due to thrombotic (local blood clot formation) or embolic (due to a blood clot or other material traveling from another site) event. "The cyclic peptide cyclo-(PheTyr), which is isolated from Sparganii Rhizoma, can alleviate ischaemic stroke reperfusion brain injury via the JunB/JNK/nuclear factor-kappaB (NF-κB) signaling pathway." (PMID 38826134, 2024). "Similarly, in ischemic stroke, JUNB/NF-κB modulation by Sparganin C promotes microglial M2 polarization, attenuating injury." (PMID 40917776, 2025).
liver cancer (3 papers, 2023 to 2025). An epithelial or non-epithelial malignant neoplasm that arises from the liver. "JUNB is documented to be low expressed in liver cancer, and a recent single-cell sequencing study reported that JUNB plays critical roles in immune response and the advances of HCC." (PMID 37397026, 2023). "This study unravels the mechanism by which fibroblasts aggravate the malignancy of liver cancer, and the results suggest that JUNB may be a target for treating liver cancer metastasis." (PMID 40253402, 2025).
lung fibrosis (3 papers, 2021 to 2025). "The Net-M5 detected genes involved in lung fibrosis (CXCL8 and IL1B), VEGFA-VEGFR2 signaling (NR4A1 and CBL), and TGF-β signaling (JUNB and ATF3)." (PMID 38259488, 2023).
osteoarthritis (3 papers, 2023 to 2025). A noninflammatory degenerative joint disease occurring chiefly in older persons, characterized by degeneration of the articular cartilage, hypertrophy of bone at the margins and changes in the synovial membrane. "In a word, JUNB/FBXO21/ERK pathway governs cartilage degeneration via blockade of autophagy in osteoarthritis, indicating that downregulation of FBXO21 might be a novel approach for osteoarthritis treatment." (PMID 37359559, 2023).
renal carcinoma (3 papers, 2015 to 2024). A carcinoma arising from the epithelium of the renal parenchyma or the renal pelvis. "Previous studies have highlighted the downregulation of CEBPD in RCC and the association of FOS and JUNB with renal cancer." (PMID 38292868, 2024).
acute myeloid leukemia (2 papers, 2007 to 2013). Acute myeloid leukemia (AML) is a group of neoplasms arising from precursor cells committed to the myeloid cell-line differentiation. "Both JunB and Jun D are located on human chromosome 19 p13.2, a region that may be involved in chromosomal translocation in acute lymphocytic leukemia (ALL), acute nonlymphocytic leukemia (ANLL) and malignant melanoma (MEL)." (PMID 17407586, 2007).
Alzheimer disease (2 papers, 2023 to 2024). A progressive, neurodegenerative disease characterized by loss of function and death of nerve cells in several areas of the brain leading to loss of cognitive function such as memory and language. "Such heterogeneity with respect to JunB expression was reported, for example, in Alzheimer’s disease, where JunB was expressed only in a specific population of an activated, highly phagocytic, stage 1 disease-associated microglia (DAM-1)." (PMID 37894348, 2023).
colorectal adenocarcinoma (2 papers, 2014 to 2021). The most common type of colorectal carcinoma. "According to the findings, in normal mucosa, both c-Jun and JunB proteins were undetectable or barely detectable, but their expression levels were dramatically enhanced in human colorectal adenocarcinomas." (PMID 34836311, 2021).
depression (2 papers, 2022 to 2026). "Within the AP-1 transcription factor family (including FOS, JUN, JUNB, and JUND), FOS expression is markedly reduced in stress-induced depressive mouse models, correlating with depression-like behaviors under chronic social defeat stress (CSDS)." (PMID 41479556, 2026).
epilepsy (2 papers, 2016 to 2020). A brain disorder characterized by episodes of abnormally increased neuronal discharge resulting in transient episodes of sensory or motor neurological dysfunction, or psychic dysfunction. "Several SRF-controlled genes that were identified in the present study (e.g., Cyr61, Bdnf, Zfp36, Fos, JunB) are upregulated in the cortex in patients who suffer from epilepsy." (PMID 25636686, 2016).
esophageal adenocarcinoma (2 papers, 2023 to 2025). A malignant tumor with glandular differentiation arising predominantly from Barrett mucosa in the lower third of the esophagus. "High JUNB expression was found to be an independent significant risk factor for poor overall survival in esophageal adenocarcinoma (hazard ratio, 1.397, 95% CI, 1.103–1.769; p = 0.005)." (PMID 40701988, 2025). "Furthermore, in the multivariate cox analysis the co-expression of cJUN and JUNB was found to be a significant risk factor for worse overall survival in esophageal adenocarcinoma (hazard ratio, 1.315, 95% CI, 1.131–1.530; p < 0.001)." (PMID 40701988, 2025).
fibrosarcoma (2 papers, 2019 to 2020). A malignant mesenchymal fibroblastic neoplasm affecting the soft tissue and bone. "Moreover, it has been shown that JUNB is induced by ALK-NPM, participating the mTOR pathway and is required for cell cycle re-entry, after quiescence, and it cooperates with c-jun for the development of fibrosarcoma." (PMID 31370904, 2019).
Insulin resistance (2 papers, 2019 to 2025). Increased resistance towards insulin, that is, diminished effectiveness of insulin in reducing blood glucose levels. "For instance, JUNB deficiency boosts adipocytes’ calorie consumption, ameliorating diet-induced insulin resistance, implying an inhibitory function of JUNB in energy metabolism." (PMID 40918148, 2025).
metabolic syndrome (2 papers, 2019 to 2025). A cluster of metabolic risk factors for CARDIOVASCULAR DISEASES and TYPE 2 DIABETES MELLITUS. "Similarly, JUNB’s connection to the IL-6 and IL-7 pathways highlights the direct link between overexpression of IL-6 and metabolic syndrome development, suggesting JUNB’s role in metabolic status regulation through IL-6 signaling modulation." (PMID 40918148, 2025).
metastatic prostate carcinoma (2 papers, 2016 to 2025). A carcinoma that arises from the prostate gland and has spread to other anatomic sites. "Low levels of JUNB in metastatic prostate cancer are associated with poor prognosis and advanced phases of prostate tumors." (PMID 28005952, 2016). "Moreover, downregulation of JUNB besides PTEN loss leads to metastatic prostate cancer." (PMID 28005952, 2016). "Among these elements are two TFs (PGR and HOXD10) in the primary and three TFs (STAT3, JUN and JUNB) in the metastatic prostate cancer network." (PMID 28005952, 2016).
metastatic tumor (2 papers, 2016 to 2019). "Among them, HOXD10 and PGR are specific to primary tumor, while STAT3, JUN and JUNB are associated to metastatic tumor based on our integrative regulatory network and survival analysis." (PMID 28005952, 2016). "On the other hand, all the examined samples (four) from metastatic tumors were positive for JUNB and the H-scores were very high (20, 120, 105, and 140)." (PMID 31370904, 2019). "Moreover, JUNB staining of 11 primary and 4 metastatic tumors from the same cohort of patients revealed a dramatic increase of JUNB expression in metastasis." (PMID 31370904, 2019). "However, all the metastatic tumors (four) were strongly positive for JUNB." (PMID 31370904, 2019).
myeloid malignancies (2 papers, 2021 to 2022). "JUNB inactivation deregulates the cell cycle machinery and increases the LT-HSCs, and JunB protects against myeloid malignancies by limiting hematopoietic stem cell proliferation and differentiation without affecting self-renewal." (PMID 34294125, 2021). "JUNB antitumorigenic activity has been shown in the myeloid lineage in transgenic mouse studies, which was consistent with JUNB repression observed in certain human myeloid malignancies." (PMID 36494864, 2022).
nasopharyngeal carcinoma (2 papers, 2019 to 2023). A carcinoma arising from the nasopharyngeal epithelium. "In lung and EBV(+) tumors such as Hodgkin’s lymphoma and nasopharyngeal carcinoma, members of the AP-1 family (cJun and JunB) were found to bind the PD-L1 promoter and induce its expression in a MAPK dependent manner." (PMID 31340499, 2019).
Obesity (2 papers, 2019 to 2021). Accumulation of substantial excess body fat. "The relationship between patient characteristics, namely, age, gender, obesity gradation, and Kellgren–Lawrence gradation and the JUNB expression in the damaged area of the cartilage are presented in the Sankey diagram." (PMID 33450132, 2021).
oral cancer (2 papers, 2017 to 2020). "However, in case of oral cancer, we observed its negative correlation particularly with JunB (P = 0.008)." (PMID 28155253, 2017).
osteosarcoma (2 papers, 2012 to 2022). A usually aggressive malignant bone-forming mesenchymal neoplasm, predominantly affecting adolescents and young adults. "This indicated that the regulation of these genes by JUNB is conserved in epithelial cancer cells other than osteosarcoma U2OS cells." (PMID 36494864, 2022). "First, depletion of JUNB in U2OS osteosarcoma cells, as well as in other epithelial cancer cells, was sufficient to reduce cell division by impairing the progression from G1 to S, leading to decreased entry into S and cell cycle arrest." (PMID 36494864, 2022).
pheochromocytoma (2 papers, 2011 to 2016). "In sum, X214L mutant protein was associated with low HIF2α expression and high JunB expression, a pattern consistent with a low risk of kidney cancer and high risk of pheochromocytoma." (PMID 20560986, 2011). "For example, disruption of pVHL binding leads to subsequent ubiquitination of aPKC-λ/ι, which in turn deregulates JunB expression and promotes tumor progression in VHL disease-related pheochromocytoma." (PMID 27530247, 2016).
prostate tumors (2 papers, 2016 to 2021). "Similarly, we also observed Fra1/2, Atf3, JunB and AP-1 binding sites are enriched in predominantly Gleason pattern 3 tumours as compared to higher grade prostate tumours." (PMID 34911933, 2021).
rheumatoid arthritis (2 papers, 2017 to 2022). A chronic, systemic autoimmune disorder characterized by inflammation in the synovial membranes and articular surfaces. "Among PSA T and NK cells, we also observed a downregulation of AP-1 transcription factors (JUN, JUNB, JUND, FOS) and regulators of activation (TNFAIP3, DUSP1) along with the upregulation of S100A11, a calcium-binding protein associated with rheumatoid arthritis." (PMID 35309349, 2022). "In patients with rheumatoid arthritis, FRA1 and JUNB were colocalized with STAT3 in the inflamed synovium." (PMID 29326694, 2017).